ALB (albumin)
Diseases named in the same sentence as ALB in open-access papers (continued):
Sharing a sentence is not in itself a finding about the gene and the disease.
coronary aneurysm (11 papers, 2015 to 2025). Abnormal balloon- or sac-like dilatation in the wall of coronary vessels. "In the multivariate analysis, presenting abdominal manifestations, age younger than 6 months, IVIG- resistance, delayed treatment and albumin concentration in the acute phase were independent risk factors for coronary aneurysms (respectively p<0.005, <0.005, = 0.005 and 0.009)." (PMID 30180185, 2018). "However, the reason for the association of serum albumin levels with coronary aneurysms and progressive coronary dilatation remains unclear." (PMID 28587647, 2017). "Univariate analysis revealed three potential risk factors associated with the coronary aneurysms, including initial maximal coronary Z-score of ≥ + 2.5, IVIG unresponsiveness, and serum albumin levels." (PMID 28587647, 2017). "The factors related to coronary aneurysm were higher platelet count (OR per 10 000 cells/μL increase: 1.01; 95% CI: 1.001–1.02), lower albumin level (OR per 1 g/dL increase: 0.34; 95% CI: 0.17–0.65)." (PMID 25716055, 2015). "The factors related to coronary aneurysm were higher platelet count (OR 1.01) and lower albumin (OR 0.34)." (PMID 25716055, 2015). "Inflammatory markers such as CRP, ESR, platelet count, hemoglobin, and albumin are key predictors of coronary artery aneurysm development, but we did not identify a significant modifying effect of biological sex." (PMID 40756547, 2025). "The median of serum albumin levels were significantly lower in the 16 KD patients with coronary aneurysms (3.4 g/dL, IQR: 2.85-3.55 g/dL) than in those without coronary aneurysms (4.0 g/dL, IQR: 3.6-4.3 g/dL; P < 0.001)." (PMID 28587647, 2017).
emphysema (11 papers, 2009 to 2025). "According to univariate analysis, old age, man, low BMI, COPD or emphysema, multiple distributions on imaging, low serum ALB, and positive sputum culture were all adverse prognosis factors for CPA, and patients with SAIA had a better outcome than CCPA." (PMID 35223906, 2022). "SAIA, old age, male, low BMI, COPD or emphysema, multiple distributions on imaging, low serum ALB, and positive sputum culture were adverse prognosis factors for CCPA and SAIA, and low BMI was an independent risk factor after adjusting for confounding factors." (PMID 35223906, 2022). "Liver growth factor (LGF) is an albumin-bilirubin complex with mitogenic properties, whose therapeutic effects have previously been reported in a model of emphysema and several rodent models of human disease." (PMID 25401951, 2014). "SAIA, old age, male, low body mass index (BMI), COPD or emphysema, multiple distribution, low serum ALB, and positive sputum culture were adverse prognosis factors for SAIA and CCPA group, and BMI ≤ 20 kg/m2 was independently associated with increased mortality." (PMID 37998889, 2023). "In the univariate analysis, sex, histological type, history of smoking, concurrent pulmonary emphysema, history of prior chemotherapy, high absolute neutrophil count, low LDH level, and high serum albumin level were found to be associated with tumor response (p < 0.1)." (PMID 19656374, 2009).
gastric varices (11 papers, 2016 to 2025). "Other findings in patients with HCV infection include a decreased incidence of esophageal and gastric varices and increased serum albumin levels during the COVID-19 era." (PMID 38310156, 2024).
gastroesophageal reflux disease (11 papers, 2021 to 2026). A chronic disorder characterized by reflux of the gastric and/or duodenal contents into the distal esophagus. "Primary endpoints included perioperative indices; time to first flatus or feeding; complications (reflux esophagitis, dumping syndrome, and Roux retention syndrome); nutritional status (hemoglobin, total protein, albumin, vitamin D, and calcium); and dietary status." (PMID 40416720, 2025). "Furthermore, low serum albumin levels, increasing age, and the presence of gastroesophageal reflux were identified as independent predictors of dysphagia." (PMID 40794188, 2025). "Two years and 8 months after the reoperation, there was no reoccurrence of reflux esophagitis without any medications, her weight increased from 44 to 59 kg, albumin increased from 3.3 to 3.7 mg/dL, and PNI increased from 41.9 to 46.3." (PMID 34928458, 2021). "The main endpoints included serum albumin and prealbumin at admission and on days 3, 7, and 14 after admission, length of ICU stay, ventilator time, and complications such as diarrhea, gastric retention, esophageal reflux, and pulmonary infection." (PMID 34580613, 2021). "Two years and 6 months after the reoperation, there was no recurrence of reflux esophagitis or related symptoms without any medications, and the patient’s weight increased from 36 to 50 kg, albumin increased from 3.1 to 4.4 mg/dL, and PNI increased from 37.8 to 53.8." (PMID 34928458, 2021).
Gastrointestinal hemorrhage (11 papers, 2018 to 2025). Hemorrhage affecting the gastrointestinal tract. "It is also possible that low albumin directly leads to compromised tissue repair and coagulation factor synthesis, which cause postoperative GI hemorrhage." (PMID 40842549, 2025). "After adjusting for all potential covariates (fully adjusted model), albumin changes were positively associated with gastrointestinal hemorrhage (OR: 0.87; 95%CI: 0.81–0.94, p < 0.001)." (PMID 39902029, 2024). "After adjusting for all potential covariates, albumin changes were negatively associated with gastrointestinal hemorrhage (OR: 0.87; 95%CI: 0.81–0.94, p < 0.001)." (PMID 39902029, 2024). "Notably, patients with gastrointestinal hemorrhage had significantly lower hemoglobin levels (92.48 ± 20.75 vs. 130.30 ± 21.96 g/L, p < 0.001) and serum albumin levels (33.70 ± 5.16 vs. 40.21 ± 5.00 g/L, p < 0.001)." (PMID 40652010, 2025). "HRS-AKI is precipitated by bacterial infection, gastrointestinal hemorrhage, large-volume paracentesis without the administration of albumin, or an acute exacerbation of alcoholic liver injury." (PMID 34070416, 2021).
Glucose intolerance (11 papers, 2013 to 2025). Glucose intolerance (GI) can be defined as dysglycemia that comprises both prediabetes and diabetes. "The inverse association between older age, glucose intolerance, and high serum albumin levels suggests a relationship with diet." (PMID 41248155, 2025). "db/db mice were characterized with glucose intolerance, high urinary albumin/creatinine ratio, and renal damage, which were found to be improved in the dapagliflozin group after 12-week treatment." (PMID 41303682, 2025). "Subclinical glucose intolerance estimated by OGTT is the second most significant prognostic factor next to serum albumin level." (PMID 37255908, 2023). "Dapagliflozin significantly relieved glucose intolerance, urinary albumin/creatinine ratio (UACR) and renal pathological injuries of db/db mice." (PMID 36213291, 2022). "According to the results above, QDD improved glucose intolerance, renal function, urinary albumin, and pathological injuries." (PMID 36091599, 2022). "Compared with 1,5-AG levels, glycated albumin and HbA1c levels have been found to provide superior discrimination for carotid wall thickness in community-dwelling Japanese subjects with glucose intolerance." (PMID 27729086, 2016). "Db/db mice had significantly high FBG, 24-hour urinary albumin, BUN, serum creatinine, UACR and obvious glucose intolerance." (PMID 36213291, 2022).
hemophilia B (11 papers, 2017 to 2025). Hemophilia B is a form of hemophilia characterized by spontaneous or prolonged hemorrhages due to factor IX deficiency. "Previously reported gene targeting strategies for hemophilia B inactivate the albumin allele, raising concerns related to the potential impact on albumin production." (PMID 35359664, 2022). "Some fusion biopharmaceutical proteins are available in the market and represent a substantial part of the drug market, such as Ontak®(IL-2 and denileukin diftitox for cutaneous T-cell lymphoma) and Idelvion® (Factor IX and albumin for hemophilia B)." (PMID 36777254, 2023). "Recently, a long-acting recombinant coagulation factor IX–albumin fusion protein (rIX-FP) has been approved for the management of hemophilia B. Fusion to albumin potentially enables internalized proteins to engage FcRn and escape lysosomal degradation." (PMID 29523681, 2018). "In an extension of the genome editing study that aimed to correct hemophilia B at the disease locus, the first intron of the albumin gene was selected for insertion of a partial hFIX cDNA." (PMID 28238287, 2017). "Both studies aimed to introduce promoterless, partial cDNAs of hFIX into the albumin locus in mouse models of hemophilia B using the liver tropic AAV serotype 8 as the delivery vector, but different regions of the Alb gene were targeted, and different editing strategies employed." (PMID 28238287, 2017). "Here, aiming at developing an efficient strategy for hemophilia B, we first treated neonate P2 wild-type and FIX KO mice with a dual rAAV vector strategy: one expressing the SaCa9/sgRNA, and one containing the donor-hFIX cDNA flanked by arms of homology for the albumin locus." (PMID 35359664, 2022).
hydronephrosis (11 papers, 2020 to 2025). Collection of urine in the renal pelvis that results in dilatation of the renal pelvis and calyces. "In this study, we found that many factors, such as the history of urological surgery, lower serum albumin, and grade of hydronephrosis, are associated with the development of COP." (PMID 36181040, 2022). "Overall, Nrf2ꜛ animals had decreased creatinine clearance, increased albumin excretion and a tendency to hydronephrosis from the outset." (PMID 36979025, 2023). "Poor prognostic indicators throughout the studies were patients who had already undergone cancer treatment, presence of multiple metastasis, type of cancer, degree of hydronephrosis, and a low serum albumin concentration." (PMID 34072127, 2021). "The results revealed that positive lymph node in imaging contributed the most to the prediction of the outcome, followed by tumor size, extravesical invasion, infiltration, grade, hydronephrosis, papillary, age, fibrinogen, NPR, creatinine, albumin, hemoglobin, and erythrocyte count." (PMID 38872141, 2024). "The univariate analysis showed significant differences in sex, fever, history of urological surgery, WBCC, neutrophils, serum CRP, serum albumin, urine leukocyte, WBCC, grade of hydronephrosis, CT value of hydronephrosis, and thick wall of the renal pelvis (P < .05) between 2 groups." (PMID 36181040, 2022).
ileus (11 papers, 2022 to 2025). Decrease in peristalsis in the absence of a mechanical bowel obstruction. "For example, the CONUT score, which incorporates albumin, cholesterol, and lymphocyte count, was linked to ileus with an AUC of 0.58 and an OR of 2.91." (PMID 40539186, 2025). "In one subject, estimated glomerular filtration rate decreased from 85 mL/min/1.73 m2 to 52 mL/min/1.73 m2), serum albumin decreased from 4.2 g/dL to 2.0 g/dL, and the other subject experiencing grade 2 ileus had neutrophilia of up to 2.7 × 1010/L." (PMID 36875713, 2022). "Old age, male gender, smoking, albumin level < 3.5 gm%, time from AWD to posterior CS + TAR surgery, SSI, ileus, and infected mesh were significantly higher in IH." (PMID 36869364, 2023). "In our experiment, on the 4th postoperative day, the mean bursting pressure in the ileus subgroup that received albumin/glutaraldehyde was higher compared to the untreated ileus subgroup, although the difference was not statistically significant." (PMID 40217906, 2025). "However, among patients with preoperative serum albumin between 3.5 and 5.5 g/dL, none had prolonged ileus, with a statistically insignificant difference in the proportion of prolonged ileus according to preoperative serum albumin (p > 0.05)." (PMID 36589182, 2022).
meningitis (11 papers, 2009 to 2025). A disorder characterized by acute inflammation of the meninges of the brain and/or spinal cord. "In our study, adults had significantly higher albumin levels than children (p = 0.001), likely reflecting the different NB manifestations, as children more often presented with meningitis and cranial nerve palsies." (PMID 40630013, 2025). "It is well established that inflammatory cytokines can contribute to BBB dysfunction in human disease, including studies of the BCSFB using albumin ratios in meningitis showing relationship to TNF- α, and cardiac surgery showing relationship to IL-6 and IL-8." (PMID 30186149, 2018). "In order to get insight into the blood-brain barrier status during meningitis, the brain/plasma albumin ratio was determined for wild-type and C/EBPδ−/− mice." (PMID 25958220, 2015). "The albumin ratio was not different between the two genotypes suggesting that C/EBPδ deficiency does not affect the disruption of the blood-brain barrier during meningitis." (PMID 25958220, 2015). "Compared to healthy children, serum albumin was lower, while serum S-100B (p < 0.05), NO, LPO, total thiol, SOD were higher in patients with meningitis." (PMID 19814795, 2009). "The patients with meningitis had increased peripheral leucocyte counts, increased levels of C-reactive protein (CRP) and CSF protein, cells and erythrocytes and a higher CSF/serum albumin ratio." (PMID 29881343, 2018). "To explore whether AKI was associated with changes in blood-brain barrier integrity, we evaluated albumin concentrations in the CSF of children with CM who had a lumbar puncture to rule out meningitis." (PMID 31109328, 2019). "The improvement of CSF parameters in the TBE group was limited at the time of examination II: median pleocytosis fell by about 30% and lymphocyte count, protein and albumin concentration, and AQ did not change, while all these parameters decreased evidently in non-TBE-meningitis patients." (PMID 28646884, 2017).
minimal change disease (11 papers, 2008 to 2025). "The expression of motor molecules, such as cytoplasmic dynein 1 and myosin IX, is increased in the podocytes under conditions of minimal change nephrotic syndrome, suggesting the enhanced transport of vesicles containing albumin." (PMID 31781392, 2019). "The mechanism underlying selective albuminuria has not been sufficiently clarified; however, several pieces of evidence from animal models indicate that FcRn-dependent albumin transcytosis is increased in minimal change nephrotic syndrome." (PMID 31781392, 2019). "The role of enhanced podocyte albumin transport needs to be investigated to elucidate the mechanism of the selective albuminuria in minimal-change disease." (PMID 22685655, 2012). "In addition, the latest KDIGO guidelines further suggested that proteinuria in GN (separate from minimal change disease) is typically heterogeneous and consists of both albumin and other proteins." (PMID 35093023, 2022). "In a non-randomized study of 14 severely edematous children with minimal change nephrotic syndrome, 20% albumin infused at an albumin dose of 0.5 g/kg over 1 h followed by furosemide reduced pretibial edema and body weight within 1 h (p < 0.05)." (PMID 18318896, 2008).
secondary hyperparathyroidism (11 papers, 2008 to 2024). Overproduction of parathyroid hormone in response to influence external to the parathyroid glands. "Generally, the recommendation for diagnosis of NCPHPT is to have normal albumin-adjusted total calcium and normal ionized calcium with elevated iPTH on at least 2 occasions over 3 to 6 months after secondary hyperparathyroidism has been excluded." (PMID 38292595, 2024). "In our study, the main factors affecting nutritional status were age, dialysis vintage, albumin level, inflammation, blood pressure, and secondary hyperparathyroidism." (PMID 36839171, 2023). "Exclusion criteria included acute or chronic bleeding, serum albumin < 35g/L, hypersensitive C-reactive protein (HsCRP) > 10 mg/L, and severe secondary hyperparathyroidism (iPTH ≥ 800 pg/mL)." (PMID 34629085, 2021). "We have applied HPLC techniques to measure the oxidized albumin ratio and to demonstrate that albumin is the predominant oxidatively modified plasma protein in HD patients with secondary hyperparathyroidism." (PMID 30450134, 2018). "Although the exact mechanism of injury remains unknown, most existing studies implicate sub-tendon bone resorption due to secondary hyperparathyroidism, in addition to chronic inflammation, as evidenced by reduced serum hemoglobin and albumin levels, which was noted in 50% of cases." (PMID 39931319, 2024).
upper tract urothelial carcinoma (11 papers, 2015 to 2025). "Although the albumin-to-globulin ratio (AGR) is a promising biomarker for various malignancies, few studies have investigated its prognostic significance for upper tract urothelial carcinoma (UTUC)." (PMID 32859201, 2020). "The combination of C-reactive protein and albumin, the Glasgow Prognostic Score (GPS), had independent prognostic value in patients with varying cancers, except for upper tract urothelial carcinoma (UTUC)." (PMID 29348903, 2017).